GRN (granulin precursor)
Diseases named in the same sentence as GRN in open-access papers (continued):
Sharing a sentence is not in itself a finding about the gene and the disease.
frontotemporal dementia (continued). "Additionally, we explored two of the three main genetic mutations associated with frontotemporal dementia (FTD)—those in the Microtubule-Associated Protein tau (MAPT) and Progranulin (GRN) genes—as FTD is a neurodegenerative condition that often affects younger populations." (PMID 40725212, 2025). "Background and objectives: Frontotemporal dementia (FTD) is a heterogeneous neurodegenerative disorder with autosomal dominant forms most often linked to MAPT, GRN, and C9orf72." (PMID 41149783, 2025). "Frontotemporal dementia (FTD) has been linked to mutations in MAPT and GRN, while vascular dementia has been linked to NOTCH3 polymorphisms that compromise vascular integrity." (PMID 40559997, 2025). "These cells expressing GBA and GRN are engrafted in murine models to ameliorate GBA deficiency-associated PD and GRN deficiency-associated frontotemporal dementia (FTD), separately." (PMID 38212785, 2024). "Mono-allelic GRN lof mutations represent 5% of all cases of Frontotemporal dementia (GRN-FTD, OMIM 607485), an adult-onset disease presenting progressive changes in behavior, personality, and language, ultimately leading to early death." (PMID 37790525, 2023). "In addition, GRN haploinsufficiency detectable in patients with frontotemporal lobar degeneration is associated with Wnt5a signaling in neuronal cells but no connection with RYK has been established." (PMID 36471440, 2022). "We report in vivo patterns of neuroinflammation and abnormal protein aggregation in seven cases of familial frontotemporal dementia (FTD) with mutations in MAPT, GRN and C9orf72 genes." (PMID 33122395, 2021). "Haploinsufficiency of the progranulin gene (GRN) is a major cause of familial frontotemporal lobar degeneration (FTLD), giving rise to a variety of fatal and untreatable frontotemporal dementia (FTD-GRN) syndromes." (PMID 31620075, 2019). "Homozygous or heterozygous mutations in the GRN gene, encoding progranulin (PGRN), cause neuronal ceroid lipofuscinosis (NCL) or frontotemporal dementia (FTD), respectively." (PMID 28828399, 2017). "The co-occurrence of the c.709-1G>A GRN mutation and the p.A152T MAPT variant has been identified in 18 Basque families affected by frontotemporal dementia (FTD)." (PMID 28594853, 2017). "Based on our current findings, we conclude that trehalose should be explored as a first-generation therapeutic treatment for frontotemporal dementia with GRN mutations as well as other neurodegenerative diseases such as AD and PD, where reduced PGRN may be a risk factor." (PMID 27341800, 2016). "Finally, besides AD, Davide V. Moretti found that EEG frequency rhythms are sensible also to different stage of Fronto-Temporal-Dementia (FTD) and could detect changes in brain oscillatory activity affected by progranulin (GRN) mutations." (PMID 27445796, 2016). "Recent research has extensively investigated the specific expression of GRN and TREM2 on microglia, the brain-resident macrophages, revealing their links to neurodegenerative disorders such as frontotemporal lobar degeneration and Alzheimer’s disease." (PMID 39143467, 2024). "A recent report from the Genetic Frontotemporal Dementia Initiative (GENFI) used multiplexed assays to measure CSF and plasma levels of complement components and activation products in FTD cases with known genetic mutations in MAPT, C9ORF or GRN at different stages of the disease." (PMID 38505993, 2024). "Subsequently, we analyzed PRDM16-DT expression in postmortem brain tissues (frontal lobe) obtained from patients with frontotemporal dementia (FTD) carrying mutations in C9ORF72, GRN, or MAPT genes, as well as from control individuals that are available via the RiMOD database." (PMID 39207536, 2024). "The most intriguing examples include GRN and FUCA1, as their loss of functions directly causes lysosomal dysregulation and neuroinflammation, accompanied by neurodegenerative disorders such as Alzheimer’s disease (AD) and frontotemporal dementia (FTD)." (PMID 38507437, 2024).
frontotemporal dementia (continued). "On the contrary, GRN haploinsufficiency leads to frontotemporal dementia (FTD), a disorder characterized by the neurodegeneration of the frontal and temporal lobes, and lysosome disfunction associated with the presence of neuronal inclusions containing fragments of ubiquitinated TDP-43." (PMID 36980592, 2023). "Homozygous GRN mutations lead to neuronal ceroid lipofuscinosis, and heterozygous mutations in GRN in humans lead to frontotemporal dementia (FTD-GRN) with TAR DNA-binding protein-positive inclusions (FTD-TDP)." (PMID 36618392, 2022). "For example, for subjects carrying the MAPT, GRN, or C90rf72 genotypes, the concentration of NFL in cerebrospinal fluid (CSF) was increased after the onset of frontotemporal dementia (FTD)." (PMID 32530970, 2020). "We also included EPHA4, for which only one functional involvement in ALS has been described recently, GRN and MAPT, which are both more likely frontotemporal dementia (FTD)-related genes." (PMID 32987860, 2020). "Mutation in one GRN allele resulting in lower levels of PGRN protein is a cause of frontotemporal lobar degeneration (FTLD) and the accompanying clinical syndrome frontotemporal dementia (FTD)." (PMID 31864418, 2019). "Moreover, deficiency of GRNs in frontotemporal dementia (FTD) caused by GRN mutations may play a causal role in the development of lysosome dysfunction that underlies FTD-GRN, which paves the way for testing GRN replacement as a therapeutic strategy." (PMID 28828399, 2017). "All seven participants with available brain autopsies (6 GRN+/A152T+, 1 GRN+/A152T-) showed frontotemporal lobar degeneration with TDP-43 inclusions (type A classification), which is characteristic of GRN carriers." (PMID 28594853, 2017). "Building on recent genetic discoveries, Julie Snowden (University of Manchester, UK) showed the relationship between the diverse clinical characteristics and the underlying pathologies of frontotemporal dementia (FTD) (tau, TDP-43 and FUS) and associated genetic mutations (MAPT, C9orf72 and GRN)." (PMID 27391874, 2015). "Compared to the GRN- and VCP-unique datasets, the FLNC-unique protein dataset showed the strongest correlation to frontotemporal dementia, neurodegeneration and aging." (PMID 26555887, 2015). "In this study, we investigated a panel of CSF synaptic markers in presymptomatic and symptomatic people with genetic FTD from the GENetic Frontotemporal dementia Initiative (GENFI), hypothesizing that we would find differential abnormalities across MAPT, GRN, and C9orf72 mutation carriers." (PMID 36045450, 2022). "Finally, genetic testing for mutations in genes commonly associated with frontotemporal lobar degeneration (FTLD) (MAPT, GRN, C9orf72) was negative." (PMID 33310885, 2020). "Given the patient’s family history of frontotemporal dementia (FTD) in a maternal uncle, the genetic analysis was extended to include the most common genes associated with FTD (TARDBP, GRN, TBK1, CHMP2B, SQSTM1, UBQLN2, VCP and MAPT) but no additional variants of clinical significance were detected." (PMID 40659544, 2025).
dementia (92 papers, 2010 to 2026). Loss of intellectual abilities interfering with an individual's social and occupational functions. "Female GRN variant carriers with MBCI or dementia at baseline exhibited faster rates of cognitive and functional decline than males." (PMID 40277077, 2025). "Frontotemporal dementia (FTD) is the second cause of dementia with an age of onset < 65, and its most common mutations are in GRN, C9orf72, and MAPT genes." (PMID 35145377, 2022). "We herein describe two sisters carrying a rare GRN mutation with extremely different clinical features and family history of dementia and behavioral disorders, with a novel presentation with stridor and dysphonia." (PMID 35859258, 2022). "We herein describe neurological features of two sisters carrying a GRN mutation with extremely different clinical phenotypes and family history of dementia and behavioral disorders." (PMID 35859258, 2022). "The Genetic Frontotemporal Dementia Initiative (GENFI) have reported that plasma levels below 61.55 ng/mL is a predictor of GRN mutations and more recently the suggested threshold was 71.0 ng/mL." (PMID 34344473, 2021). "In the patients that do have a highly positive family history of dementia, mutation in the progranulin (GRN) or expansion of the chromosome 9 open reading frame 72 (C9ORF72) gene have been described." (PMID 27915998, 2016). "Taken together these results support the concept of fronto-parietal dementia, calling for a new nosology of the disease related to GRN mutation." (PMID 25188321, 2014). "Pathogenic mutations in APP, PSEN1, PSEN2, MAPT and GRN have previously been linked to familial early onset forms of dementia." (PMID 22312439, 2012). "In addition, we also detected another three VUS in several autosomal dominant genes which can lead to other types of dementia or are recognized as risk factors for AD, such as GRN and SORL1." (PMID 37051054, 2023). "This hypometabolism pre-dates dementia in FTD linked Granulin (GRN) mutant carriers, spreads as disease progresses and in Microtubule-Associated Protein Tau (MAPT) -linked FTD patients closely maps to areas of toxic MAPT accumulation, suggesting it closely tracks disease development." (PMID 37733679, 2023). "Finally, specific single nucleotide variants in GRN have been shown to decrease plasma and brain expression levels of PGRN and are risk factors for Alzheimer’s disease (AD), the most common form of dementia." (PMID 34618685, 2021). "We aimed to investigate mutation‐specific white matter (WM) integrity changes in presymptomatic and symptomatic mutation carriers of the C9orf72,MAPT, and GRN mutations by use of diffusion‐weighted imaging within the Genetic Frontotemporal dementia Initiative (GENFI) study." (PMID 30250860, 2018). "Our report extends the evidence for genetic and phenotypic variability in FTLD disorders, and detects a novel pathogenic GRN mutation, carriers of which could eventually help to evaluate the efficacy of different treatments at early stages of dementia." (PMID 26961809, 2016). "We report here our investigations into another dementia-causing gene, GRN, and identify phagocytic receptors MERTK and AXL as part of the pathogenesis of GRN dysregulation." (PMID 40596721, 2025). "Heterozygous mutations in the GRN gene that result in PGRN haploinsufficiency cause FTLD, the second most common cause of dementia in people under the age of 65." (PMID 40713630, 2025). "Another notable finding is the identification of GRN p.R556C in a dementia case with an AAO of mid-30s." (PMID 40813364, 2025). "Another notable finding is the identification of GRN p.R556C in a dementia case with an AAO in her mid-30s." (PMID 39606324, 2024). "Although this variant has been widely reported across different types of dementia, our finding is the first report of this variant in DLB with a McKeith criteria of “high likelihood of DLB,” expanding the etiological spectrum of GRN variation." (PMID 39606324, 2024).
dementia (continued). "Subjects carrying heterozygous GRN LOF mutations develop early onset FTLD-TDP, a neurodegenerative disease considered the second most common cause of dementia after AD." (PMID 36978829, 2023). "Levels of GRN expression were found to be lower in parietal regions of AD patients with the rs5848 T allele, and in a sample of controls, AD, FTD, and other dementias, homozygous carriers of the rs5848 T allele had the lowest levels of serum PGRN." (PMID 37958929, 2023). "No additional variants were detected in PSEN2, APP, or other dementia causative genes (e.g., MAPT, GRN, and TARDBP)." (PMID 35932032, 2022). "As mentioned in the Results section, this second cluster includes genes that have also been related to other dementia types (e.g., GRN, TMEM107B, SNX1, MAPT, CTSB and CTSH)." (PMID 36066633, 2022). "A family history of dementia is found in 25–50% of the FTD patients with microtubule-associated protein tau (MAPT) and progranulin (GRN) mutations, and chromosome 9 open-reading-frame 72 (C9orf72) expansion as major pathogenetic determinants." (PMID 35672480, 2022). "Our data support the pathogenic role of GRN p.R298H variant in FTD, since it was first found in two Italian sisters with FTD and family history of behavioral disturbances and dementia." (PMID 35859258, 2022). "We analyzed baseline visit data of known carriers of a pathogenic variant in the c9orf72, GRN, or MAPT gene from the Genetic Frontotemporal Dementia Initiative cohort study." (PMID 35948443, 2022). "Here, we evaluate BMAA exposure by investigating transcription signatures using PCR for dolphin genes homologous to those implicated in AD and related dementias: APP, PSEN1, PSEN2, MAPT, GRN, TARDBP, and C9orf72." (PMID 34678990, 2021). "There is some evidence of genetic moderation of apathy in dementia, such as the apolipoprotein E gene (APOE) ε4 allele in Alzheimer's disease, as well as C9orf72 and GRN mutations in FTD." (PMID 33316852, 2021). "The clinical spectrum of FTD associated with GRN mutations includes the behavioural variant (bvFTD), primary progressive aphasia (PPA), and dementia associated with movement disorders such as parkinsonism including corticobasal syndrome." (PMID 27632209, 2016). "In summary, a complete screening for mutations in MAPT, GRN and C9ORF72 genes revealed a frequency of 5.4% of pathogenic mutations in a random cohort of 93 Turkish index patients with dementia." (PMID 27632209, 2016). "As expected, patients with GRN+ had a higher rate of positive family history for dementia (91.7%) than those with GRN- (40%, P=0.008)." (PMID 24040338, 2013). "There were no genome-wide or suggestive associations with genetic variants in known causal Mendelian dementia genes (APP, PSEN1, PSEN2, and GRN), suggesting that common variants in these genes do not significantly contribute to sporadic EOAD, or that we do not have enough power." (PMID 38883718, 2024). "A recent GWAS for AD and related dementias (ADRD), which pooled AD cases with “proxy cases” having a family history of all-cause dementia, used colocalization analysis to provide evidence that ADRD and FTD with TDP-43 inclusions share causal variants at the TMEM106B and GRN loci." (PMID 37328865, 2023). "Specifically, GRN carriers had a tendency of a faster increase of mean and radial diffusivity values and C9orf72 carriers had a tendency of a faster decline of fractional anisotropy values as they reached closer to the expected age of dementia onset." (PMID 36632182, 2022). "Two families were negative for DIAD variants or other genes associated with autosomal dominant cause of dementia (e.g., MAPT, GRN, TARDBP, FUS), probands on those families were APOE4 carriers; 11 families are undergoing additional genetic counseling for future genetic testing." (PMID 35932032, 2022). "Additionally, three studies reported associations in non‐AD dementias, namely, DLB and FTD patients with GRN, C9orf72 and MAPT mutations." (PMID 35338546, 2022).
dementia (continued). "In the Genetic Frontotemporal Dementia Initiative (GENFI), only symptomatic GRN mutation carriers were found to have an increased global load of WMH when compared to normal controls, presymptomatic GRN mutation carriers, and both presymptomatic and symptomatic C9orf72 and MAPT mutation carriers." (PMID 34256835, 2021). "In this work, we combined gene expression data for 16 772 genes from the Allen Institute for Brain Science atlas with brain maps of grey matter atrophy in symptomatic C9orf72, GRN and MAPT mutation carriers obtained from the Genetic Frontotemporal dementia Initiative study." (PMID 33210084, 2020). "These included two GRN+/A152T+ patients with dementia affecting multiple cognitive domains." (PMID 28594853, 2017). "Taken together these results suggest a possible involvement of miR-659-3p in GRN up-regulation mediated by hypoxic/ischemic insults and confirm the importance to study the regulation mechanism of GRN expression after hypoxic insult in order to understand its role in dementia." (PMID 27199656, 2016). "Given the frequency of variants identified in MAPT, GRN and C9ORF72, but also in our previous analysis of PSEN1, PSEN2 and APP, in the Turkish cohort of dementia patients studied, a standardized molecular screening procedure for these genes should be implemented in Turkey." (PMID 27632209, 2016). "Characteristics of the cohort of dementia patients analysed for mutations in MAPT, GRN and C9ORF72." (PMID 27632209, 2016). "Furthermore, additional proteins which were consistently altered in both the FLNC-, GRN- and VCP-unique datasets, e.g. GFAP, NPTN, DBI, PRDX6, MARCKS and BSN, are closely associated with cognitive function, dementia and pathological aging." (PMID 26555887, 2015). "This analysis revealed that variants in the PSEN1 (HR = 6.2; 4.6–8.2) and GRN (HR = 9.9; 5.0–19.6) genes significantly increased the risk of dementia (data not shown)." (PMID 25333068, 2014). "Moreover, the combination of calsyntenin-1 with other synaptic proteins has shown a potential ability to discriminate FTLD subtypes from other type of dementias, such as FTLD TDP-43-subtype from AD and healthy subjects, and GRN/C9orf72 pre-symptomatic mutation carriers from mutation non-carriers." (PMID 39000564, 2024). "This changed in 2012, when a complete deficiency of progranulin, caused by a homozygous GRN loss-of-function mutation, was reported in two siblings diagnosed with adult-onset neuronal ceroid lipofuscinosis (NCL) type 11, presenting with visual loss, dementia and epilepsy." (PMID 36009452, 2022). "When these data is combined with data we have previously published we conclude that among 105 dementia patients, 5.7% are attributable to PSEN1 mutations (6/105), 2.9% (3/105) to C9ORF72 and TREM2 each, and 0.95% (1/105) to MAPT, GRN and NOTCH3 each, while 85.7% (90/105) remain unclear." (PMID 27632209, 2016). "Therefore we investigated whether MAPT, GRN and C9ORF72 gene mutations are major contributors to dementia in a random, unselected Turkish cohort of dementia patients." (PMID 27632209, 2016). "Other important hubs and pathway connections include the GRN protein, which bridges AD pathways to neuronal cell death and blood–brain barrier (BBB) disruption, other hallmarks of this dementia." (PMID 33946285, 2021). "Examples of these cohorts are the GENetic Frontotemporal Dementia Initiative (GENFI; genotype data for GRN, MAPT, and C9ORF72 genes) and the Genetic and Environmental Risk in Alzheimer’s Disease (GERAD) Consortium (whole exome sequences)." (PMID 34559060, 2021). "Using this tool, we performed thalamus segmentations in MRI scans from C9orf72, GRN and MAPT mutation carriers and mutation non-carriers with suitable 3-Tesla MRI cross-sectional data from the GENetic Frontotemporal dementia Initiative." (PMID 41245435, 2025).